TMPRSS2 (transmembrane serine protease 2)
Diseases named in the same sentence as TMPRSS2 in open-access papers (continued):
Sharing a sentence is not in itself a finding about the gene and the disease.
prostate carcinoma (continued). "Gene fusions involving the androgen-regulated gene TMPRSS2 and ERG, a member of the ETS family of transcription factors, occur in about 50% of prostate cancers, especially in young patients, and result in strong ERG protein overexpression." (PMID 24261794, 2013). "The fusion through deletion TMPRSS2-ERG rearrangement results in a well-defined 3-Mbp interstitial deletion on chromosome 21 and occurs in approximately 50% of prostate cancer cases." (PMID 23561577, 2013). "We thus propose that overexpression of TDRD1, observed by us and others in 100% of TMPRSS2:ERG-positive prostate tumors, makes TDRD1 a promising target for immunotherapy of ERG rearrangement-positive prostate cancer." (PMID 23555854, 2013). "Our previous expression profiling study of human prostate cancer specimens revealed that TDRD1 is, apart from ERG, the most differentially expressed gene between TMPRSS2:ERG-negative and -positive tumors." (PMID 23555854, 2013). "This advancement in technology facilitated the detection of further fusions, e.g. the EML4-ALK fusion in lung cancer and the TMPRSS2-ERG fusion in prostate cancer." (PMID 23341502, 2013). "Tudor domain-containing protein 1 gene (TDRD1) was reported to be differentially expressed between TMPRSS2:ERG-negative and TMPRSS2:ERG-positive prostate cancer." (PMID 23555854, 2013). "For example, the expression of both chimeric TMPRSS2-ERG and SLC45A3-ELK4 are androgen-regulated in prostate cancer, a male and androgen-sensitive cancer." (PMID 24243830, 2013). "In prostate cancer, fusion of ETS-related genes (in most cases, the ERG) with AR-regulated gene promoter of TMPRSS2 is present in approximately 50% of prostate tumors." (PMID 23466879, 2013). "TMPRSS2/ERG rearrangement, PTEN gene deletion, and androgen receptor (AR) gene amplification have been observed in various stages of human prostate cancer." (PMID 24098661, 2013). "While the TMPRSS2:ETV1 fusion is rare and occurs in 1–10% of prostate cancers, the TMPRSS2:ERG fusion is present in roughly half of prostate cancers and is the most common genetic aberration so far described in prostate cancer." (PMID 23957008, 2013). "TMPRSS2/ERG fusion gene indirectly up-regulates ZEB2, a facilitator of the epithelial to mesenchymal transition (EMT), by binding to IL1R2 to increase prostate cancer tumorigenesis." (PMID 24359571, 2013). "Extensive investigation remains in order to understand the TMPRSS2:ERG gene fusion products role in prostate cancer progression, but it is clear that this molecular event is an early and important marker of prostate cancer." (PMID 22641253, 2012). "Prostate cancer derived urine exosomes are shown to contain two known prostate cancer biomarkers, PCA-3 and TMPRSS2: ERG, showing the potential for diagnosis and monitoring cancer patient’s status." (PMID 25419445, 2012). "Primary prostate epithelial cells demonstrated increased post transcriptional turnover of ERG compared to the TMPRSS2-ERG positive VCaP cell line, originally isolated from a prostate cancer metastasis." (PMID 22860005, 2012). "Cancer outlier profile analysis (COPA) has proven to be an effective approach to analyzing cancer expression data, leading to the discovery of the TMPRSS2 and ETS family gene fusion events in prostate cancer." (PMID 23216803, 2012). "ERG mRNA is not expressed in healthy prostate tissues, but as a result of the TMPRSS2-ERG gene fusion early in carcinogenesis, a significant increase in ERG transcript levels can be detected in prostate cancers." (PMID 22761906, 2012). "The most frequent genomic rearrangement in prostate cancer is fusion of the Ets transcription factor, Ets related gene (ERG), with the promoter of the highly-expressed transmembrane protease serine 2 (TMPRSS2) gene." (PMID 22860005, 2012). "Other seminal plasma proteases with matrix-regulation activities include TMPRSS2 (the most common fusion partner of ERG), HPN and PSA, all previously shown to be up-regulated in prostate cancer." (PMID 21814574, 2011).
prostate carcinoma (continued). "Especially TMPRSS2 fuses with ERG and Ets family genes such as ETV1, ETV4 and ETV5 in prostate cancers." (PMID 21347291, 2011). "For ETS gene fusions in prostate cancer, the androgen-responsive regulatory elements of TMPRSS2 drive the expression of the ETS family member to which TMPRSS2 is fused." (PMID 21625565, 2011). "The TMPRSS2-ERG gene fusion results in the modulation of transcriptional patterns and cellular pathways with potential consequences for prostate cancer progression." (PMID 22142399, 2011). "Although the TMPRSS2-ERG fusion is a critical early and common event in prostate cancer development and progression, the clinical implications of the fusion are controversial and the functional consequences are unclear." (PMID 22142399, 2011). "In human prostate cancer, genomic alterations of ETS-related genes, principally ERG, often occur as fusions between an androgen receptor-regulated gene promoter of TMPRSS2 and ETS transcription factors and are detected in about 50% of tumors." (PMID 22110995, 2011). "CTCs were successfully enriched and detected in men with advanced prostate cancer using an immunomagnetic enrichment procedure coupled with amplified molecular assays for PSA, PCA3, and TMPRSS2:ERG gene fusion mRNAs." (PMID 20598135, 2010). "As a proof-of-concept, we show the presence of two known prostate cancer biomarkers, PCA-3 and TMPRSS2:ERG the in exosomes isolated from urine of patients, showing the potential for diagnosis and monitoring cancer patients status." (PMID 19401683, 2009). "Fusion of the androgen-regulated gene, TMPRSS2, with ERG occurs in up to 60% of prostate cancers and is likely to account for the majority of ETS oncogene rearrangements in prostate cancer." (PMID 19223900, 2009). "Using this array, proof of principle was demonstrated by detection of known fusion genes (such as TCF3:PBX1, ETV6:RUNX1, and TMPRSS2:ERG) from all six positive controls consisting of leukemia cell lines and prostate cancer biopsies." (PMID 19152679, 2009). "It is possible that like the fusions between TMPRSS2 and ERG, ETV1, ETV4 and ETV5, other functionally identical fusions are involved in changes in gene expression and prostate cancer development but are yet to be discovered." (PMID 18694509, 2008). "The reported incidence of TMPRSS2:ETV1 fusion in these studies (1–2%) was, however, considerably lower than the observed incidence of ETV1 gene overexpression (∼10% in prostate cancer)." (PMID 18594527, 2008). "We included oligonucleotide probe sets for the three major members of the ets family involved in prostate cancer: ERG, ETV1, and ETV4, as well as their translocation partner TMPRSS2." (PMID 18846227, 2008). "Our panel(s) included probe sets for three members of the ets family involved in prostate cancer; ERG, ETV1, and ETV4, as well as their translocation partner, TMPRSS2." (PMID 18846227, 2008). "They found that TMPRSS2-ERG could inhibit neuroendocrine and tubulointerstitial cell differentiation, thereby promoting prostate cancer proliferation." (PMID 40584293, 2025). "Prostate cancer patients receiving ADT showed significantly reduced pulmonary TMPRSS2 expression compared to non-ADT patients (mean histoscores: 152.7 vs. 225.0, p = 0.037) and age-matched women controls (mean histoscores: 152.7 vs. 238.0, p = 0.024)." (PMID 41150771, 2025). "Considering the link between HSPs and AR activity, we next investigated the impact of NXP800 on AR signaling, demonstrating a decrease in AR-FL and AR-V7 protein expression, and also in expression of AR-responsive genes (KLK2, KLK3, TMPRSS2, and FKBP5), across all three prostate cancer cell lines." (PMID 39787247, 2025). "A positive TMPRSS2-ERG test result in urine suggests the presence of prostate cancer, although it does not necessarily indicate its aggressive nature." (PMID 41374944, 2025).
prostate carcinoma (continued). "TMPRSS2::ERG, the hallmark fusion of prostate cancer, failed to be reported by both LongGF and FusionSeeker, while CTAT-LR-Fusion detects 45, 98, and 104 long isoform reads supporting TMPRSS2::ERG across the three sequenced libraries." (PMID 40086881, 2025). "The quantitative assessment showed significantly reduced TMPRSS2 protein expression in prostate cancer patients receiving ADT compared to those not receiving ADT (mean histoscores: 152.7 vs. 225.0, p = 0.037)." (PMID 41150771, 2025). "Notably, the TMPRSS2-ERG fusion, which is present in approximately 50% of prostate cancers, leads to an AR-mediated upregulation of ERG signaling and is implicated in pathways that lead to metastasis rather than cell growth." (PMID 40075623, 2025). "It has been postulated that the short distance between the TMPRSS2 and ERG genes on the chromosome 21 could account for the higher frequency of TMPRSS2:ERG fusions in prostate cancer." (PMID 40332527, 2025). "sGCα1 and sGCβ1 expression was also shown to be specifically and directly regulated by transmembrane protease serine 2 (TMPRSS2):v-ets erythroblastosis virus E26 oncogene homolog (ERG), also known as TMPRSS2:ERG or T2E (TMPRSS2-ERG), in PCa prostate cancer cells." (PMID 39337539, 2024). "In the first instance, we screened a large panel of coregulators in the DEGs between TMPRSS2 fusion positive and negative prostate cancer in EA and AA patients in the TCGA prostate cancer cohort (TCGA-PRAD)." (PMID 37082578, 2023). "This identified 27 altered coregulators in AA patients, and from these, five were uniquely or more significantly altered in AA compared with EA TMPRSS2 fusion negative prostate cancer." (PMID 37082578, 2023). "TMPRSS2, a key gene mediating the entry of SARS-CoV-2 into humans, is highly expressed in prostate cancer and its high expression could promote the development of prostate cancer." (PMID 36875081, 2023). "Thus, about half of all cases of prostate cancer have a fused TMPRSS2-ERG transcript, which is formed due to an intrachromosomal rearrangement leading to the fusion of two genes: TMPRSS2 and ERG." (PMID 37298233, 2023). "The TMPRSS2:ERG gene fusion, which is recognized as one of the most common gene fusions found in prostate cancer patients, was identified in 15 of 44 patients (34%), slightly lower than a previously reported estimate of 42.6% in metastatic castrate resistant-prostate cancers." (PMID 38050021, 2023). "The TMPRSS2–ERG fusion is uniquely present in prostate cancer in approximately 50% of the cases; however, it does not occur upon lack of AR signaling." (PMID 35954292, 2022). "TMPRSS2 is part of the type 2 transmembrane serine protease (TTSP) family and has been extensively studied in the context of prostate cancer as its expression is regulated in response to androgens through direct transcriptional regulation by the androgen receptor (AR)." (PMID 36560732, 2022). "DNA damage caused by genotoxic agents, such as docetaxel, CPT and IR, may lead to the degradation of normal ERG and TMPRSS2–ERG proteins in a SPOP-independent manner, suppressing prostate cancer." (PMID 35954292, 2022). "In addition, androgen and genotoxic stress recruit cytidine deaminase (AID) and LINE1-encoded ORF2 endonuclease to the specific sites and induce DNA cleavage of TMPRSS2, SLC45A3, ERG, and ETV1 in prostate cancer." (PMID 36579559, 2022). "Among them, TMPRSS2-ERG (e2e4) was expressed higher in tumors and its expression predicted poor prognosis in TCGA prostate cancer study, whereas its parental genes had no such association." (PMID 36088396, 2022). "In prostate cancer, ERG often forms a fusion gene with transmembrane protease, serine 2 (TMPRSS2)." (PMID 35954308, 2022).
prostate carcinoma (continued). "Furthermore, TMPRSS2 has been shown to activate the single-chain precursor of hepatocyte growth factor (HGF), which contributes to prostate cancer metastasis." (PMID 35163273, 2022). "TMPRSS2-ERG and other rearrangements in prostate cancer cells may result from a molecular accident accompanying AR recruitment of the topoisomerase TOP2B to regulatory sequences near target genes during transcriptional activation." (PMID 35104804, 2022). "For example, previous studies have reported the detection of fusion between TMPRSS2 and ERG in prostate cancer tissues, and high expression of PSMA in advanced PC or mCRPC tissues which is related to related to higher tumor stage/Gleason score/preoperative PSA levels." (PMID 35402423, 2022). "Despite initial promise in pre-clinical models, reports regarding the efficacy of androgen-targeted therapies in prostate cancer patients harboring TMPRSS2-ERG gene fusions have not been conclusive." (PMID 36212399, 2022). "In prostate cancer, different genomic rearrangements can occur, such as the most common fusion of androgen receptor TMPRSS2 with ERG. miR-204 is a TMPRSS2/ERG oncofusion negative regulator and can act as a tumor suppressor or oncomiR, regulating the genes under androgen receptor control." (PMID 34204705, 2021). "The most prevalent genetic rearrangement in prostate cancer involves the fusion of the androgen-regulated gene TMPRSS2 with the ETS transcription factor ERG, which is estimated to occur in ~50% of prostate cancer cases being by far the single most common genetic fusion gene in solid tumors." (PMID 33634124, 2021). "Androgen deprivation therapy (ADT) has been theorized to decrease the severity of SARS-CoV-2 infection in patients with prostate cancer owing to a potential decrease in the tissue-based expression of the SARS-CoV-2 coreceptor transmembrane protease, serine 2 (TMPRSS2)." (PMID 34767021, 2021). "TMPRSS2:ERG gene fusions are also specific to prostate cancer and can be detected in urine, but are absent in about 50% of patients with prostate cancer." (PMID 34576294, 2021). "Furthermore, the high expression of host cell protease TMPRSS2 promotes SARS-CoV-2 fusion in both localized and metastatic prostate cancers." (PMID 33391502, 2021). "Moreover, TMPRSS2 tends to form a fusion with ERG, which is present in 40-80% prostate cancers and promotes cell migration and metastasis of prostate cancer." (PMID 34168096, 2021). "The reason for the frequent presence of the TMPRSS2:ERG (T2E) gene fusion in prostate cancer (PCa) is not fully understood." (PMID 33669024, 2021). "TMPRSS2 has an important role in the pathogenesis of COVID‐19, and the abnormal expression of TMPRSS2 or ERG gene fusion is significant regulators of carcinogenesis in prostate cancer." (PMID 33609069, 2021). "Interestingly, the expression of the TMPRSS2-ERG fusion gene changed the chemical and radio reactivity of androgen-independent prostate cancer cells." (PMID 34381020, 2021). "The TMPRSS2–ERG gene fusion and subsequent overexpression of the ERG transcription factor occurs in ∼50% of prostate tumors, making it the most common abnormality of the prostate cancer genome." (PMID 33554122, 2021). "In contrast to high prevalence in Caucasians, the prevalence of TMPRSS2-ERG in Chinese population is very low, while the prevalence of PCA3 is high in Chinese population and the increased expression has been reported in Chinese prostate cancer patients." (PMID 32099679, 2020). "Results of an in vivo study in these cells showed a significantly reduced expression of TMPRSS2 in malignant cells harboring TMPRSS2–ERG fusion, but not in prostate cancer cells without TMPRSS2–ERG fusion." (PMID 33243086, 2020).
prostate carcinoma (continued). "Notably, recurrent gene fusions of the 5′ untranslated region of TMPRSS2 to the transcription factor ERG is the most frequent genomic alteration in early- and late-stage prostate cancer and results in overexpression of ERG." (PMID 32450906, 2020). "The presence of the TMPRSS2:ERG fusion was demonstrated by next-generation sequencing on both malignancies, leading to the assumption that the lung nodule was a metastasis from the prostate cancer." (PMID 33419298, 2020). "Recently, it is shown that the oncogenic transcription factor ERG, expressed by the TMPRSS2:ERG fusion gene, could upregulate the AKR1C3 expression in prostate cancer." (PMID 32226548, 2020). "The results of our analysis demonstrate that SFRP4 up-regulation is an independent predictor of early PSA recurrence in prostate cancers lacking TMPRSS2:ERG fusions." (PMID 32677026, 2020). "The results of our study demonstrate that upregulation of hnRNPA1 is associated with adverse tumor features and poor prognosis in the subset of prostate cancers lacking TMPRSS2:ERG fusions." (PMID 32417965, 2020). "However, while numerous studies have been performed, since its discovery, the role of the TMPRSS2-ERG fusion, in prostate cancer development and progression, is not yet fully understood." (PMID 31275657, 2019). "According to the ensemble of these observations, it was concluded that ERG activation, induced by the TMPRSS2-ERG rearrangement, has an important role in prostate cancer progression and cooperates with PTEN haploinsufficiency to promote prostate cancer progression." (PMID 31366128, 2019). "Clinically, exosomes derived from the urine of patients with prostate cancer have also been documented to display specific prostate cancer mRNA biomarkers, such as prostate cancer antigen 3 and transmembrane protease serine 2:transforming protein ERG (TMPRSS2:ERG)." (PMID 31078138, 2019). "Strong SNW1 expression was markedly more frequent in prostate cancers harboring the TMPRSS2:ERG fusion (24%) than in ERG negative cancers (7%, p < 0.0001)." (PMID 31043167, 2019). "As seen in prostate cancer, the forced expression of normal proteins (i.e. 3′ gene, ETS family of transcription factors) through an androgen-responsive promoter (TMPRSS2, a transmembrane serine protease) or by fusion to ubiquitous promoters results in overexpression of a wild-type protein." (PMID 31007851, 2019). "While TMPRSS2-ERG status still was a major discriminating feature in the integrative clustering analyses, we identified a third thus far unknown prostate cancer subtype that contained both high and low ERG expression samples." (PMID 30464211, 2018). "That PSCA expression was completely unrelated to TMPRSS2:ERG fusion further demonstrates that PSCA is not significantly affected by any of the hundreds of genes that are deregulated in ERG fusion positive prostate cancer." (PMID 29855276, 2018). "In prostate cancer, many genes from the ETS family participate in fusion transcripts with transmembrane serine protease isoform 2 (TMPRSS2); in fact, three ETS members (ERG, ETV1, and ETV4) contribute to about 80% of TMPRSS2 fusion." (PMID 29455655, 2018). "Most prostate carcinomas exhibit deletions (less commonly translocations) on chromosome 21q that activate ETS-family transcription factors, usually via an N-terminal fusion with the androgen receptor (AR)-activated gene TMPRSS2." (PMID 29671777, 2018). "One example of this consistency is TMPRSS2-ERG, a clinical marker for prostate cancer." (PMID 30340508, 2018).